RB1 (RB transcriptional corepressor 1)
Diseases named in the same sentence as RB1 in open-access papers (continued):
Sharing a sentence is not in itself a finding about the gene and the disease.
adenocarcinoma (continued). "Several of the identified mGISTIC regions harbored known or putative adenocarcinoma driver candidates, such as EGFR, MDM2, KRAS, MYC, TERT, MET, CCND1, NKX2-1/TITF1, CDK4, ERBB2, ID1, RB1, CDKN2A and PTEN." (PMID 24205279, 2013). "Cases with RB1 alterations have not been reported by major case series or a recent study of 15 cases limited to mixed‐type ductal adenocarcinomas with a common clonal origin." (PMID 36573306, 2023). "Additionally, while SCLCs often harbor mutations in or loss of the retinoblastoma gene (RB1), RB1 loss is necessary but not sufficient for SCLC development from adenocarcinomas." (PMID 39456595, 2024).
infection (64 papers, 2007 to 2025). The state of being infected such as from the introduction of a foreign agent such as serum, vaccine, antigenic substance or organism. "We then induced the expression of the latent Kras allele in both the control mice (LSL-Kras, Rb1+/+) and our compound mutant mice using Ad-Cre by intranasal infection." (PMID 23936539, 2013). "Following infection by all sensitive and resistant strains, bcl2 and rb1 expressions were statistically significantly up-regulated, while bad and bax expressions were significantly down-regulated 24 and 48 hr post-infection." (PMID 38800030, 2024). "As compared with strains with the New-1 genotype (INHR, RifR, MDR, and XDR), the Beijing genotype (sensitive isolate) significantly increased and decreased anti-apoptotic (bcl2 and rb1) and pro-apoptotic genes (bad and bax) 24 and 48 hr post-infection." (PMID 38800030, 2024). "Among five samples which showed diffuse strong positive expression in p16 IHC, all had wild type form of CDKN2A, while three had RB1 frameshift insertion mutation and the other two had high-risk HPV (type 16) infection." (PMID 38902320, 2024). "Significant reduction in lung virus titers of the Rb1 group was observed on day 3 post infection when compared with the titers in the mock control group (P < 0.001)." (PMID 28187149, 2017). "DF-1 cells were infected with rLS-RFP or rB1-GFP and super infected with rB1-GFP or rLS-RFP at different intervals post-primary infection, respectively (1, 3, 12 and 24 h pi)." (PMID 23034005, 2012). "We generated a recombinant NDV strain LaSota, encoding the red fluorescent protein (RFP; rLS-RFP) and used it in co-infection assays with a related strain of NDV (B1) expressing the green fluorescent protein (GFP; rB1-GFP)." (PMID 23034005, 2012). "NN1172-infection leads to the down-regulation of many genes related to cell cycle and DNA replication genes, including MCM 2 ~ 6, CDK1 ~ 2, CCNB2, ANAPC2, MAD2L1, WEE1, RBL1, RB1." (PMID 38362295, 2024). "For both genes, the global rate of methylation was higher when the virus was present: 32.4% for RB1 in the presence of HPV vs. 15.3% without virus detection, and 25.0% for CDH1 with HPV and EBV infection vs. 15.3% with no infection." (PMID 26032781, 2015).
colon NEC (7 papers, 2017 to 2025).
metabolic disorders (7 papers, 2015 to 2024). "Rb1 treatment ameliorated metabolic disorders in HFD-fed mice, accompanied by altered gut microbiota, fecal lipid profiles, and colonic gene expression." (PMID 35516426, 2022). "In this study, we found Rb1 has a beneficial effect on the improvement of metabolic disorders both in mice and rats." (PMID 35516426, 2022). "However, little is known about the effect of Rb1 on the energy metabolic disorders and changes in mitochondria induced by I/R challenge." (PMID 28327605, 2017). "Interestingly, Rb1 treatment protected all these I/R-induced energy metabolism disorders in myocardium, as well as myocardium impairment, which pointed to the potential of Rb1 to relieve the disordered energy metabolism by regulation of ATP5D expression and ATP synthase activity." (PMID 28327605, 2017). "Taken together, these results demonstrate that oral administration of Rb1 modulates gut microbes, which is beneficial to improve HFD-induced metabolic disorder." (PMID 35516426, 2022).
benign tumor (6 papers, 2009 to 2024). "Its causative gene, RB1, has opened the way to the two-hit theory, the limitations of which have been highlighted by the study of retinoma, a benign tumor." (PMID 19390654, 2009). "Retinocytomas are benign tumors that arise from mutations in the RB1 gene." (PMID 39493168, 2024). "The main ones include other benign tumors with RB1 deletion such as spindle cell lipoma (SCL) and cellular angiofibroma (CAF)." (PMID 33802620, 2021).
cardiovascular disease (6 papers, 2014 to 2025). "The findings presented here also highlight the potential clinical applications of Rb1 in controlling resistin-associated vascular injury and the possible therapeutic use in cardiovascular disease." (PMID 37304947, 2023).
neurodegenerative disease (4 papers, 2017 to 2025). A disorder of the central nervous system characterized by gradual and progressive loss of neural tissue and neurologic function. "Consistent with this, we also detected the rate of RB1 heterozygous mutations in blood samples from neurodegenerative disease patients." (PMID 38637503, 2024). "In this study, we recognized RB1 mutations in 2–3% of neurodegenerative diseases by analyzing clinical sequencing data." (PMID 38637503, 2024). "Taken together, we recognized RB1 mutations was 2–3% in neurodegenerative diseases by analyzing clinical sequencing data." (PMID 38637503, 2024). "Interestingly, hyperphosphorylation of RB1, a negative regulator of the cell cycle, is associated with neurodegenerative diseases." (PMID 38637503, 2024). "Therefore, we used zrb1-KO mutants to verify the effect of R621S/L819V alterations (a statistical significance mutation in neurodegenerative diseases) in human RB1 on neuronal apoptosis." (PMID 38637503, 2024). "In this study, we identified several RB1 mutations in patients with neurodegenerative diseases." (PMID 38637503, 2024). "The mechanism of action may be to prevent tau hyperphosphorylation by modulating glycogen synthase kinase 3β and protein phosphatase levels, suggesting that Rb1 is a potential prophylactic drug for AD and other neurodegenerative diseases associated with tau pathology." (PMID 31416121, 2019). "As apoptosis is a prominent feature in a broad spectrum of neurodegenerative diseases, we investigate the role of Rb1 in neuronal apoptosis." (PMID 38637503, 2024). "To clarify the role of RB1 in neuronal apoptosis and neurodegenerative diseases, we first analyzed blood sequencing data from patients with neurodegenerative diseases." (PMID 38637503, 2024). "Growing body of evidence indicates that Rb1 has a protective effect on neural tissues related to inflammatory and degenerative diseases." (PMID 28900459, 2017). "In the turquoise module, four hub lncRNAs (Gm5848, Zfp141, Rmrp, and Rb1) linked to hub mRNAs (Psmb3, Mad211, Sdhd, Ndufa6, Snrqd2, and Immp11) and are mainly related to NAFLD, multiple neurodegenerative diseases, oxidative phosphorylation, cell cycle, inflammation, and metabolic pathways." (PMID 40141450, 2025). "Knockout of Nrmt1 in mice led to the inactivation of RB1 and eventually induced neurodegenerative diseases, while the AD-related gene presenilin 1 (PS1) could protect the anaphase neuronal death by inhibiting the phosphorylation of RB1." (PMID 38637503, 2024).
CNS tumors (3 papers, 2022 to 2024). "PBTC-042 was a phase I open-label dose-escalation trial to assess the maximum tolerated dose (MTD) and pharmacokinetics of daily oral PD-0332991 (Palbociclib isethionate) in Rb1+ recurrent, progressive, or refractory primary CNS tumors in young adults (NCT02255461)." (PMID 35936751, 2022).
colon (3 papers, 2015 to 2025).
kidney diseases (3 papers, 2024 to 2025). "Abundant evidence has confirmed that Rb1 is therapeutic in multiple kidney diseases such as AKI, CKD and DKD and can improve kidney function and pathological injury." (PMID 40682486, 2025). "Among them were several genes known to be involved in kidney diseases, such as Kdm5a, Rb1, Tead1, Xbp1 and Ppargc1α with so far unknown role as sexual dimorphism regulators." (PMID 39278930, 2024). "Notably, it has been demonstrated that Rb1 can mitigate CKD‐related vascular calcification by inhibiting the Wnt/β‐catenin pathway, suggesting that Rb1 may promote vascular repair in kidney diseases." (PMID 40682486, 2025).
neurological disorders (3 papers, 2010 to 2024). "It is possible that different types of RB1 mutations can induce proliferative and apoptotic neurological diseases by altering different binding proteins." (PMID 38637503, 2024). "This study clarified the specific effects and molecular mechanisms of Rb1 on activation and regulation of the neuronal apoptosis program and provided a reference for the pathogenesis of Rb1-related neurological diseases." (PMID 38637503, 2024).
central nervous system diseases (2 papers, 2017 to 2019). "Rb1 is increasingly recognized as an important neurotrophic factor, with potential for application in ameliorating central nervous system disorders." (PMID 31572200, 2019).
head and neck tumors (2 papers, 2013).
epithelial neoplasm (1 paper, 2025). A benign or malignant neoplasm that arises from and is composed of epithelial cells.
hematologic cancers (1 paper, 2023). "In hematopoietic cancer cells, IFN-β signaling can directly restore RB1 function by increasing its gene expression or protein activation with reduction of its phosphorylation to induce an RB1-mediated G1/G0 growth arrest." (PMID 37182173, 2023). "In hematologic cancers, IFN-β and IFN-α can induce a potent RB1-mediated G1/G0 growth arrest, implying that they are more sensitive to an IFN-based therapy." (PMID 37182173, 2023).
nervous system tumours (1 paper, 2003). "Loss of 13q arm has been found in about 0–30% of solid tumours, including nervous system neoplasms in which up to 45% of GB display loss at the RB1 locus." (PMID 12556968, 2003).
RB1 also shares sentences with these, for which no sentence is quoted: oropharyngeal carcinoma (9 papers); adenomyosis (8); cervical dysplasia (7); multiple myeloma (7); oral squamous cell carcinoma (7); laryngeal carcinoma (6); renal carcinoma (6); adenovirus infection (5); embryonal tumors (5); esophageal squamous cell carcinoma (5); medullary thyroid carcinomas (5); myxofibrosarcoma (5); pediatric tumor (5); uveal melanoma (5); Burkitt lymphoma (4); Ewing sarcoma (4); genetic disease (4); human papilloma virus infection (4); mantle cell lymphoma (4); pancreatic ductal adenocarcinoma (4); anal carcinoma (3); bone cancer (3); Crohn disease (3); diabetic retinopathy (3); Fibroadenoma (3); gastric adenocarcinoma (3); hepatitis C (3); invasive carcinoma (3); large cell neuroendocrine carcinomas of the lung (3); liver fibrosis (3).
A further 233 diseases each share a sentence with RB1 in 3 papers or fewer.